RN7SL66P (RNA, 7SL, cytoplasmic 66, pseudogene)
Gene: Miscellaneous RNA gene on chromosome 2 (10,280,628 to 10,280,891, forward strand). Ensembl gene ENSG00000264030.
Homologues: Orthologues: macaque Metazoa_SRP (19% identical). Paralogues in human: RN7SL163P (40% identical), RN7SL811P (38% identical), RN7SL96P (38% identical), Metazoa_SRP (37% identical), RN7SL744P (37% identical), Metazoa_SRP (36% identical), RN7SL391P (35% identical), Metazoa_SRP (35% identical), RN7SL134P (35% identical), RN7SL274P (35% identical), RN7SL693P (35% identical), RN7SL371P (34% identical), and 691 more.